CXCL12 (C-X-C motif chemokine ligand 12)
Diseases named in the same sentence as CXCL12 in open-access papers (continued):
Sharing a sentence is not in itself a finding about the gene and the disease.
breast carcinoma (continued). "Moreover, miR-126/miR-126* reduces the lung metastatic potential of breast cancer by inhibiting the expression of CXCL12, thereby blocking the recruitment of MSCs to the tumor ECM." (PMID 28356139, 2017). "Indeed, the chemokine CXCL12 plays critical roles in cell migration, angiogenesis, proliferation, and survival in many types of cancer, including breast cancer, by interacting with the transmembrane receptors CXCR4 and CXCR7." (PMID 28666461, 2017). "For instance, our analysis identified promoter hypermethylation and underexpression of ligand CXCL12 in six cancer types, and previous studies have reported epigenetically induced silencing of this gene in breast cancer, colon cancer and non-small cell lung cancers." (PMID 27899617, 2017). "Similarly CXCL12, a ligand of both CXCR4 and ACKR3, is associated with advanced breast cancer in humans, and is expressed at high levels during puberty and pregnancy in our study (data not shown)." (PMID 27888192, 2017). "Also, it is intriguing that GRK3 not only controlled survival and proliferation of breast cancer cells but also promoted primary breast cancer invasion and metastasis by dysregulated signaling through CXCL12/CXCR4." (PMID 29445249, 2017). "Based on these observations, anti-CXCL12 strategies may represent an innovative approach for targeting mammary tumors abundantly expressing myoepithelial and stromal CXCL12." (PMID 29240722, 2017). "On the other hand, CXCR4 activation triggered VEGF-dependent neoangiogenesis in glioma and breast cancer cells, suggesting that CXCL12 may synergize with other pro-angiogenic factors to induce the formation of new blood vessels." (PMID 29240722, 2017). "Indeed, breast cancer cells metastasize preferentially to CXCL12-rich tissues such as the lungs and bone marrow." (PMID 26993780, 2016). "In a recent report, supported the hypothesis that CXCL12-CXCr4 axis promotes the natural selection of breast cancer cell metastasis with implications for tumor aggressiveness." (PMID 27526676, 2016). "The role of chemokine receptors in metastatic organ selectivity was first reported for CXCR4, a receptor that stimulates metastasis of breast cancer and melanoma cells to the lung and lymph node where its ligand, CXCL12 (also known as SDF-1: stromal cell-derived factor 1), is abundant." (PMID 27136535, 2016). "Furthermore, being consistent with TSHZ2-mediated suppression of CXCR4 expression, we found that CXCL12-induced breast cancer cell migration was inhibited by the expression of TSHZ2 but neither LacZ nor TSHZ2del4." (PMID 26744317, 2016). "Furthermore, CAFs have also been reported to secrete high levels of CXCL12 which were demonstrated to enhance the proliferation of breast cancer cells." (PMID 27782035, 2016). "Breast cancer metastasis is known to be mediated in part by the CXCL12/CXCR4 signaling axis." (PMID 27049755, 2016). "Thus, the significance of the CXCL12/CXCR4 axis in breast cancer invasion and metastasis has been widely investigated." (PMID 26161302, 2015). "In summary, here we show that breast cancer cell-derived ANGPTL2 may play important roles in bone metastasis by enhancing responsiveness of breast cancer cells to bone tissue-secreted CXCL12 through up-regulated tumor cell CXCR4 expression." (PMID 25773070, 2015). "This evidence first identified a key function of CXCR4/CXCL12 in metastatic breast cancer." (PMID 27429863, 2015). "Supporting this hypothesis, CXCL12 expression was a strong independent prognostic biomarker for better survival in breast cancers, and administration of CXCL12 has been suggested as a potent inhibitor of colorectal and melanoma metastasis." (PMID 25704881, 2015). "The CXCL12-specific miRNAs, including miR-127, −197, −222 and −223, which are transported from bone marrow-derived stromal cells to breast cancer cells via gap junctions or stromal-derived exosomes, promote breast cancer cell quiescence by a decrease in CXCL12 levels." (PMID 26146543, 2015).
breast carcinoma (continued). "In addition to having a higher affinity for the migration surface and CXCR4, CXCL12-γ is present at lower levels within the tumor environment, and lower levels of CXCL12 correlate with increased metastasis in mouse models and worse prognosis in breast cancer." (PMID 25909600, 2015). "Furthermore, our findings suggest that in bone tissue, CXCL12-activated CXCR4 signaling in breast cancer cells induced by ANGPTL2 also accelerates osteolysis and bone engraftment." (PMID 25773070, 2015). "The importance of the TGF-β and CXCL12 loops is well explained in breast cancer." (PMID 24978438, 2014). "With regard to brain metastasis, it remains unknown how cancer cells breach the brain-blood barrier (BBB) and invade this tissue, but it is possible that CXCL12-expressing CNS cells are chemoattractants for metastatic breast cancer cells." (PMID 25165728, 2014). "Moreover, we observed significant increases in ERK and STAT3 phosphorylation in 4T1.2 breast cancer cells on CXCL12 induction." (PMID 24886617, 2014). "Autocrine CXCL12 has similar pre-clinical effects in lung cancer progression andhas been correlated with positive clinical outcomes in patients with osteosarcoma or breast cancers." (PMID 24594697, 2014). "Given this dichotomy between the physiologic and pathophysiologic functions of CXCR4, we hypothesized the constitutive expression of CXCL12 may play a pivotal role in determining the function of CXCR4 signaling in the human breast cancer." (PMID 24810923, 2014). "Blocking CXCR4/CXCL12-induced signaling can slow down the breast cancer growth and metastasis." (PMID 24810923, 2014). "Also, Overexpression of CXCL12 increased in-vitro invasion and migration of human breast cancer MDA-MB-231 cells." (PMID 25237365, 2014). "In addition, CXCL12 (SDF-1) was recently shown to promote CD8+ cytotoxic T lymphocyte activity when overexpressed in a syngeneic model of breast carcinoma." (PMID 25165728, 2014). "Supporting these data, our clinicopathological study revealed that patients with co-expression of CXCR4 and CXCL12 tend to have positive lymph node metastasis and clinical progression of TNM stage, suggesting that CXCR4-CXCL12 axis is a significant prognostic marker in breast cancer patients." (PMID 24810923, 2014). "Moreover, our results show for the first time that CXCL12 expression is negatively regulated by EGF signaling in breast cancer cells." (PMID 24906407, 2014). "Interestingly, in breast cancer cells the synthesis and release of CXCL12 is under the control of 17β-estradiol contributing to its proliferative effects and mediating, via a Src-dependent mechanism, EGFR transactivation." (PMID 25484899, 2014). "In this study, we observed that CXCL12 enhances CXCR7-mediated breast cancer migration." (PMID 24886617, 2014). "However VDA-associated hypoxia eventually also resulted in elevated CXCL12 levels and increased TEM infiltration in mammary tumor models." (PMID 25051364, 2014). "For example, CXCL14 derived from CAFs in prostate cancer and SDF1/CXCL12 derived from CAFs in breast cancer called up macrophages, endothelial cells derived from bone marrow source, M2 mononuclear cells to the tumor tissue respectively, which assisted the tumor formation new blood and lymph vessels." (PMID 23577100, 2013). "Since their actions influence gene expression, microarray analysis could be employed as it has been done to investigate CXCL12 induced signaling in T cells, breast cancer or glioma cells." (PMID 23322021, 2013). "CXCL12/CXCR4 axis is supposed to be crucial in brain metastasis formation from breast cancer." (PMID 23322021, 2013). "Moreover, Subik and coworkers recently reported that the ubiquitin E3 ligase WWP1 can negatively regulate cell migration to CXCL12 by limiting CXCR4 degradation to promote breast cancer metastasis to bone." (PMID 23472074, 2013).
breast carcinoma (continued). "Indeed, in breast cancer high levels of expression of CXCL12 were shown in organs representing the first destination for breast cancer metastasis." (PMID 22415233, 2012). "The coinjection of CAFs and MCF-7 breast cancer cells into nude mice resulted in the recruitment of bone-marrow-derived endothelial progenitors in response to CAF-derived stromal cell derived factor (SDF1/CXCL12) stimulating angiogenesis and tumor formation." (PMID 22482059, 2012). "Muller and colleagues have shown that chemokine receptors CXCR4 and CXCR7 are highly expressed in human breast cancer specimens, while their corresponding ligands CXCL12/SDF-1alpha (stromal cell-derived factor) and CCL21/6Ckine showed peak levels in primary breast cancer destination sites." (PMID 22746994, 2012). "Among these miRNAs are those that target CXCL12, which pass from stroma to breast cancer cells." (PMID 22482060, 2012). "A decline in CXCL12 production correlates with decreased breast cancer cell proliferation." (PMID 22482060, 2012). "The physiological stimuli driving amoeboid motility in cancer cells both in vitro and in vivo have yet to be identified; however, CXCL12 supports blebbing and amoeboid motility and CXCL12 is highly expressed in tissues that are prevalent sites of distant breast cancer metastasis." (PMID 23024796, 2012). "Reduced expression of CXCR4 in metastatic lesions as compared to corresponding primary tumors has been reported in breast carcinoma, and hypothesized to be due to CXCL12-induced internalization and degradation and/or lower microenvironmental HIF-1α levels." (PMID 23249693, 2012). "CXCL12 is highly expressed in tissues that are prevalent sites of distant breast cancer metastasis." (PMID 23024796, 2012). "Furthermore, expression of CXCR4 and CXCL12 predicts lymph node metastasis in colorectal, oesophageal and breast cancer." (PMID 22415233, 2012). "Recent studies find that the induction of vessel narrowing, hypoxia, and hemorrhagic necrosis in murine mammary tumors by vascular disrupting agents, such as combretastatin A4, is accompanied by elevated tumor levels of the chemokine CXCL12 and tumor cell repopulation." (PMID 23056181, 2012). "To examine whether the CXCL12 signaling axis may be differentially regulated by ER ligands in breast cancer cells, we examined the effects of several xeno-estrogens on the expression of CXCL12, CXCR4 and CXCR7 in MCF-7 cells." (PMID 21695171, 2011). "CAFs can enhance tumor growth in a paracrine manner, with secreted CXCL12 directly stimulating growth of CXCR4 expressing breast cancer cells, and in an endocrine manner, recruiting endothelial progenitor cells (EPCs) to the primary tumors, thus enhancing angiogenesis." (PMID 22152016, 2011). "Together, these results suggest that the epigenetic regulation by DNA methylation of both the CXCR4 and CXCL12 genes in breast cancer could serve as a potential biomarker to indicate patient prognosis." (PMID 22220212, 2011). "The role of the CXCR4/CXCL12 axis in breast cancer metastasis has been well documented." (PMID 24212798, 2011). "For example, while CXCL12 is associated with a good prognosis in non-basal breast cancers (log rank test P = 0.002), but no such correlation is seen for basal cancers (P = 0.688)." (PMID 21521526, 2011). "The E2-induced up-regulation of the chemokine CXCL12 and its receptor CXCR4 and down-regulation of CXCR7 could be associated with the effect of estrogens on the growth of breast cancer cells." (PMID 21695171, 2011). "Our results showed that the E2-dependent up-regulation of CXCL12 and CXCR4 that is associated with a down-regulation of CXCR7 could be pivotal for E2-induced growth of breast cancer cells." (PMID 21695171, 2011). "During cancer progression, the hormonal control of the CXCL12 signaling axis in breast cancer cells may therefore play major roles in tumor growth and the suppression of the invasion potential of cancer cells." (PMID 21695171, 2011).
breast carcinoma (continued). "Our results suggest that JWH-015-mediated effects of p44/p42 ERK, focal adhesion formation, and actin stress fiber polymerization may lead to reduced CXCL12-induced motility and wound healing capability of breast cancer cells." (PMID 21915267, 2011). "In the present study, we have analyzed the effects of synthetic non-psychoactive cannabinoid JWH-015 that specifically binds to CB2 receptors on breast cancer and have shown that this compound inhibits CXCL12/CXCR4-induced breast cancer invasive properties in vitro." (PMID 21915267, 2011). "While CXCL12 expression is associated with a favourable prognosis in an analysis of all breast cancers, there may be significant heterogeneity in the impact of CXCL12 on tumour behaviour between subtypes." (PMID 21521526, 2011). "Alternatively, as suggested by our prior report of increased proliferation in CXCL12-expressing human breast cancer cells, differential sensitivity to anoikis may point toward carcinoma-specific roles for CXCL12 in modulating carcinogenesis." (PMID 20877573, 2010). "CXCL12 is also known to be present in the organs that are target for metastasis in breast cancer." (PMID 20109227, 2010). "The results presented here show that epigenetic alterations might play an important role in the downregulation of CXCL12 mRNA in breast cancers in Brazilian women." (PMID 20109227, 2010). "High levels of CXCL12 are expressed by parenchymal cells in organs commonly affected by metastatic breast cancer, such as liver, bone, and brain, suggesting that gradients of CXCL12 regulate homing of disseminated breast cancer cells to endothelium in these sites." (PMID 19484126, 2009). "While CXCR4 or CXCR7 expression on circulating breast cancer cells increased adhesion to endothelium, CXCL12-dependent enhancements in adhesion or adhesion selectivity were, surprisingly, statistically the same (p = 0.48) and therefore independent of expression of CXCR4 or CXCR7 on cancer cells." (PMID 19484126, 2009). "Surprisingly however, we have found that DIMand genistein downregulate CXCR4 and CXCL12 in both ER+ and ER− cell lines,indicating that these phytochemicals may be effective in the treatment of bothearly- and late-stage breast cancers." (PMID 19325924, 2009). "Activation of CXCR4/CXCL-12 signaling plays a critical role in growth and invasion of primary and metastatic breast tumors; CXCR-4 expression is a hallmark of a subset of stem breast cancer cells, with metastatic behavior and homing to bone." (PMID 19226458, 2009). "In addition, approximately twice as many MDA-MB-231 (231-control) breast cancer cells adhere onto the endothelium when the endothelium is treated with CXCL12 basally compared to apically." (PMID 19484126, 2009). "Crucially,the ligand CXCL12 was highly expressed in tissues taken from human organ sitesto which breast cancer cells metastasize, including lymph nodes, lung, liver,and bone marrow, but expressed at low levels in tissues that represent raresites of metastasis, including the kidney, skin, and muscle." (PMID 18779872, 2008). "While CXCR4 and another chemokine receptor, CCR7, are highly expressed on the surface of human breast cancer cells, CXCL12 and a CCR7 ligand, CCL21, are highly expressed in lymph nodes, bone marrow, lung and liver, which form the common metastatic destinations of breast cancer." (PMID 19787093, 2008). "However, except for CXCR4/CXCL12, little is known about the relation between tumour-related chemokine expression and the development and progression of solid tumours like breast cancer." (PMID 18781150, 2008). "The foundation forour appreciation of the role that CXCR4 and CXCL12 may play in cancermetastasis was set in 2001, when a landmark study by Albert Zlotnik'sgroup demonstrated the importance of the CXCL12/CXCR4 axis in site-specificmetastasis of breast cancer." (PMID 18779872, 2008).
breast carcinoma (continued). "Muller reported that CXCL12 could increase the concentration of F-actin in breast cancer cells in vivo, thus facilitate the breast cancer cells' migration and invasion in a specific direction." (PMID 18983683, 2008). "In breast cancer the prognostic influence of HER2/neu was shown to be at least partly based on increased metastatic potential mediated by the chemokine–chemokine receptor pair SDF-1(CXCL12)/CXCR4." (PMID 17245339, 2007). "In addition, organs commonly associated with being sites of breast cancer metastasis, such as lung, liver, lymph node, brain and bone, constitutively express the sole ligand for CXCR4, CXCL12." (PMID 17726466, 2007). "Indeed, it has recently been shown that carcinoma-associated fibroblasts secrete CXCL12 and therewith stimulate tumour proliferation directly by acting through CXCR4 found on the breast cancer cells." (PMID 16189523, 2005). "Therefore, it appears that the final distribution of metastases in breast cancer reflects the relative abundance of CXCL12 in the different organs." (PMID 11953881, 2002). "Cell adhesion molecules such as ICAM, B1 integrin, PECAM-1, P-selectin, CXCL12, and SDF-1 have also been proposed as part of the mechanism underlying breast carcinoma metastasis, and ICAM expression in meningiomas may also facilitate adhesion of metastases to meningioma blood vessels." (PMID 39099765, 2024). "Furthermore, CB activation could interfere with breast cancer bone metastasis via C-X-C motif chemokine ligand 12 (CXCL12) and C-X-C motif chemokine receptor 4 (CXCR4) pathway." (PMID 39527598, 2024). "Because the TGF-β/SMAD3 signaling can upregulate CXCR4 expression in breast cancer, promoting metastasis, and its ligand CXCL12 is enriched in the bone marrow microenvironment, we evaluated whether SOST silencing could change in the expression of these factors in SCP2 cells." (PMID 36581888, 2022). "Also, in human breast cancers, the CXCL12 signaling was shown to induce their malignant phenotypes." (PMID 35300413, 2022). "In addition, CXCL12/CXCR4 can increase the malignancy of breast cancer and cervical cancer." (PMID 35768705, 2022). "In addition, nanobubbles created by the combination of AMD070 with the light-absorbing material indocyanine green (ICG) were found to block the interaction of CXCL12 with CXCR4 in breast cancer cells, thereby inhibiting the growth of cancer cells and promoting the apoptosis." (PMID 35893797, 2022). "Here the authors show that Brca1 deficiency in preclinical breast cancer models is associated with the accumulation of myeloid derived suppressive cells and resistance to immune checkpoint blockade, that could be overcome by targeting S100A9 and CXCL12." (PMID 35304461, 2022). "However, HER2 was shown to promote the CXCL12/CXCR4/AKT axis only in breast cancer." (PMID 34064589, 2021). "Moreover, other computational approaches such as information theory that has recently been applied in the field of biological signal transduction could be beneficial to study the role of the CXCL12/CXCR4 pathway in breast cancer pathogenesis." (PMID 33096815, 2020). "It has been demonstrated that CXCL12 is able to induce angiogenesis by recruiting endothelial progenitor cells in breast cancer (BC), thereby providing sufficient nutrients to guarantee tumor growth and metastasis in vivo." (PMID 32466591, 2020). "Indeed, in breast cancer patients it was reported that low serum CXCL12 levels may favor the migration of tumor cells overexpressing CXCR4, predicting and promoting the development of distant metastases." (PMID 30012106, 2018). "Encouraged by the significant inhibitory effects of E5 on the CXCR4/CXCL12 axis, in this work, we applied E5 to breast cancer cells and mouse models to investigate whether E5 could sensitize breast cancer cells to chemotherapeutics and to reveal its underlying mechanisms." (PMID 29263923, 2017).